CD44 (CD44 molecule (IN blood group))
Diseases named in the same sentence as CD44 in open-access papers (continued):
Sharing a sentence is not in itself a finding about the gene and the disease.
pneumonia (15 papers, 2015 to 2025). An acute, acute and chronic, or chronic inflammation focally or diffusely affecting the lung parenchyma, caused by an infection in one or both of the lungs (by bacteria, viruses, fungi, or mycoplasma.). "In agreement, neutrophil accumulation in the lungs of CD44-deficient mice infected with E. coli-induced pneumonia is more intense than in lungs of corresponding WT mice." (PMID 26624007, 2015). "The role of CD44 in the acute phase (6 h after infection) of pneumonia caused by Escherichia coli and Streptococcus pneumoniae differed significantly as reported in a previous study." (PMID 25954275, 2015). "A number of studies have implicated CD44 in the progression of bacterial infection and in the amelioration of lung inflammation in pneumonia models." (PMID 25954275, 2015). "The study showed that when compared to wild type mice, E. coli-induced pneumonia in CD44-deficient mice causes increased lung inflammation, as evidenced by increased neutrophil accumulation, migration, and increased mRNA levels of inflammatory genes." (PMID 25954275, 2015). "However, results of studies using Cd44-deficient mice showed increased lung inflammation in response to E. coli-induced pneumonia." (PMID 39095775, 2024). "However, CD44‐deficient mice exhibited increased lung inflammation and elevated proinflammatory cytokine release in E. coli‐induced pneumonia and peritonitis, respectively." (PMID 36336784, 2022). "Our data revealed that γδ T cells in the lungs of animals surviving neonatal pneumonia exhibited an activated CD69+CD44+CD62L- profile, consistent with tissue-resident effector T cells." (PMID 41011451, 2025). "Unlike E.coli based pneumonia, S. pneumonia and Klebsiella pneumonia induced pneumonia shows decreased CD44–HA-mediated signalling and downstream activation of inflammatory pathways." (PMID 34980167, 2022). "Administration of MSC EV with an anti-CD44 Ab largely abolished the therapeutic effects of the EV in a severe pneumonia model in vivo." (PMID 34016170, 2021). "Elevated HA production in bronchioalveolar lavage fluid was detected from CD44 KO mice with pneumonia." (PMID 31226944, 2019). "In a mice model of K.pneumoniae induced pneumonia, increased neutrophil numbers in lungs from CD44 KO mice occurred during both lethal and sublethal pneumonia." (PMID 31226944, 2019). "A later study explored this scenario and found transient increases in inflammation in CD44 knockout mice at lower doses of S. pneumoniae-induced pneumonia." (PMID 25954275, 2015). "Similarly in pneumonia, CD44 plays a positive but opposite role in the advancement of infection instigated by Escherichia coli and Streptococcus species." (PMID 34980167, 2022). "Evidenced to easily enter macrophages via CD44 mediated endocytosis, therapeutic efficacy of these micelles was then tested in vivo in pneumonia-induced mice infected with Staphylococcus aureus, which showed greatest bactericidal effect in the group with HA-NO-LF and NO-stimulus present." (PMID 36110312, 2022). "Additionally, OASCLR could target inflammatory macrophages by the interaction of OASCLR with the macrophage binding site of CD44 and alleviate overactive immune responses for hyperactive immunocompetent pneumonia." (PMID 36817841, 2023). "Using this approach, we found significantly more LkT/C+ CD44+ CD4+ T cells in mice that recovered from SSTI, compared with those that recovered from pneumonia, thus confirming that only SSTI elicited S. aureus-specific memory CD4+ T cells." (PMID 35983063, 2022). "It is found that the immune landscape of the lungs in mice recovered from severe pneumonia was significantly reshaped, which was characterized by a significant decline in the frequency of naïve T cells (CD62L+CD44-) along with the accumulation of highly differentiated memory T cells (CD62L-CD44+)." (PMID 37490715, 2023). "Pneumonia induced by high doses of Streptococcus pneumoniae, however, was not affected by absence of CD44." (PMID 30540779, 2018).
pneumonia (continued). "In the current proposal, we hypothesized that HMW HA primed MSC EV would increase the trafficking of the EV to the injured alveolus in severe PA pneumonia, increasing the overall interaction of MSC EV with target cells in part through CD44 expression on the EV." (PMID 34016170, 2021). "An additional study showed that mice lacking CD44 with pneumonia had reduced bacterial dissemination and higher survival rates at lethal bacterial doses, suggesting CD44 signaling is important for reducing lung inflammation and increasing the spread of bacterial infection." (PMID 31226944, 2019).
meningioma (14 papers, 2013 to 2025). A generally slow growing tumor attached to the dura mater. "For instance, CD44 is a possible CSCs marker in meningioma; the high expression of CD44 was associated with a shorter progression‐free survival." (PMID 38783892, 2024). "Also, CD44 could be one of the promising biomarkers that might differentiate high-risk meningioma patients for better treatment management." (PMID 39725765, 2024). "Sudanese meningioma patients have shown inconsistent expression of stem cell markers such as CD44, CD73 and CD105 in different meningioma samples." (PMID 39316249, 2025). "The inactivation, mutation, or loss of NF2 in meningiomas leads to loss of NF2 tumor suppressor activity, most notably by way of altered E-Cadherin expression, CD44-mediated cell–cell contact inhibition, and the Hippo signaling pathway." (PMID 39796693, 2024). "With somatic mutations of NF2, Merlin loses its tumor suppressive regulation of cell–cell contact inhibition through CD44, contributing to the formation of sporadic meningiomas." (PMID 39796693, 2024). "Our results from FACS showed the expression pattern of the cancer stem cell markers CD44/CD133 in an atypical meningioma cell line." (PMID 32742192, 2020). "The atypical meningioma-derived cell line showed enhanced expression of CD44 in all the cells including CD133+ and CD133− cell subpopulations." (PMID 32742192, 2020). "In this regard, TiMa of both −22/22q− and cytogenetically complex meningiomas also showed higher expression of both the CD44 and CD9 adhesion molecules vs diploid cases." (PMID 24098347, 2013). "Furthermore, in meningioma, the level of CD44 expression is correlated with the grade of the tumor and its invasiveness." (PMID 38783892, 2024). "CD44 has been reported to be expressed more frequently in higher graded meningiomas." (PMID 38023177, 2023). "The sorted double-positive subpopulations (CD44+/CD133+) derived from the atypical meningioma cell line showed a significantly shorter population doubling (PD) time compared to the CD44+CD133− populations, suggesting extensive proliferation and stem-like properties of the CD133+ cells." (PMID 32742192, 2020). "Additionally, flow cytometry and sorting assays were conducted to investigate and isolate the CD133 and CD44 positive cells from primary atypical meningioma cells." (PMID 32742192, 2020). "Additionally, we used the cell adhesion molecule CD44, previously shown to be expressed on meningioma tumour cells, to support the large variation in immune filtrates by gating tumour cells (CD45−HLA-DR−CD14−CD44+) at each time point." (PMID 32070062, 2020). "Further, we performed FACS analysis to analyze the expression of CD44 and CD133, which are known cancer stem cell (CSC) markers and have been proposed as candidate meningioma CSCs markers." (PMID 32742192, 2020). "KLF4K409Q tumours showed upregulation of CD44, a cell surface receptor interacting with matrix metallopeptidase 9 (MMP9) and positively correlated with proliferation, which is upregulated in higher-grade meningiomas." (PMID 40562609, 2025). "Although the CD44+/CD133+ dual-positive phenotype may imply a stem-like feature of the model, further validation studies are necessary to determine whether our atypical meningioma-derived primary cell lines meet the criteria of CSCs and are suitable for studies on cancer stem cell biology." (PMID 32742192, 2020).
astrocytoma (13 papers, 2012 to 2025). "Similar findings have been reported previously with CD44 in astrocytomas where CD44 deficiency led to decreased angiogenesis in mouse model." (PMID 29914429, 2018). "In this respect, our results are contradictory to a previous report where CD44 expression was increased in high grade compared to low grade astrocytomas." (PMID 29914429, 2018). "In contrast, CD44 was expressed by a majority of astrocytoma cells (in vivo) and ependymoma cells (in vitro and in vivo)." (PMID 26183281, 2015). "Furthermore, astrocytes in human AD brains were described to express CD44, and an astrocytoma cell line exposed to amyloid-beta increased CD44 expression in vitro." (PMID 30241479, 2018). "Angiogenesis might be one way by which hyaluronan and CD44 induce aggressive behavior in diffusely infiltrating astrocytomas." (PMID 29914429, 2018). "Moreover, it has been reported that in high grade astrocytomas (grades III-IV) the expression of CD44 is elevated." (PMID 29914429, 2018). "Similarly, we have previously observed that the apoptosis of astrocytoma induced by these triterpenes was accompanied by cytoskeletal protein rearrangements, as well as an altered expression of CD44, a molecule which facilitates cell-cell and cell-extracellular matrix communication." (PMID 22844495, 2012). "Our findings substantiate a model for T cell exclusion in IDHmt astrocytoma in which microglia produce SPP1 and IL-1β, thereby enabling crosstalk with CD44 and IL-1R-positive GTCs, a process that is highly reminiscent of glial scarring." (PMID 39880824, 2025). "Histologically, high CD44 expression is detected in GBM, and less frequently in astrocytoma, oligodendroglioma, or oligoastrocytoma." (PMID 36989359, 2023). "Immunofluorescence analyses further suggested that CD44 is highly expressed in GBM while virtually absent in LGG (astrocytoma WHO grade II)." (PMID 38414005, 2024).
fibrosis (13 papers, 2013 to 2025). the formation of excess fibrous connective tissue in an organ or tissue in a reparative or reactive process. "In addition, CS PGs, including VCAN and CD44, have been implicated in both hepatic fibrosis and HCC formation." (PMID 36923282, 2022). "Across all three settings, key profibrotic markers (FAPα, CD44, S100A9, CTGF and PDGF) were increased under TOX exposure or established fibrosis and were reduced either by RAGE antibody treatment or by clinical improvement." (PMID 41410848, 2025). "Fibrosis and HCC: Our RNAseq analysis of the livers from Efcab4b−/− mice exhibit downregulation of the macrophage marker CD163, the CD44 antigen and Lymphocyte antigen 96 (Ly96) and upregulation of beta-1, 4-galactosyltransferase 1 (B4GALT1)." (PMID 40034259, 2025).
liver disease (13 papers, 2013 to 2026). "In liver disease, it has been shown that CD44 expression is significantly elevated and associated with pathogenesis by impacting cellular responses, such as metabolism, proliferation, differentiation, and activation, in different cells." (PMID 38731968, 2024). "The development of liver disease is strongly associated with the disruption of metabolic homeostasis, and there is growing evidence suggesting that CD44 is involved in the regulation of glucose and lipid metabolism in the liver." (PMID 38731968, 2024). "Taken together, these data demonstrate that HA binding to CD44 may represent an important step in progression of inflammation associated with LD induced liver disease." (PMID 23762326, 2013). "Although the involvement of CD44 in liver disease has been suggested, most research has focused on its role in cancer, while its impact on non-cancerous liver conditions, such as metabolism, fibrosis, and inflammation, is often underestimated." (PMID 38731968, 2024). "The increased expression and cleavage of CD44 can disrupt metabolic homeostasis and exacerbate inflammation and fibrosis in liver disease." (PMID 38731968, 2024). "Hepatic CD44 expression was reported to be upregulated in the fibrotic livers of patients with various liver diseases, such as viral hepatitis and NASH." (PMID 38790021, 2024). "CD44 has been studied in numerous diseases, including cancer, infections, lung disease, vascular disease, and liver disease." (PMID 38731968, 2024). "Additional studies are necessary to investigate the therapeutic potential of HA-based CD44 targeting systems in liver disease." (PMID 36930869, 2023). "Overall, our data provides evidence that the variables, TIPRL, LC3, CD133, and CD44, have a prominent effect on a prognostic role in liver disease/cancer patients." (PMID 34208132, 2021). "Contrarily, we discovered the upregulation of CD133, CD46, and CD44 in liver disease tissues, except for cirrhosis." (PMID 34208132, 2021). "For the assessment, we stained tissues of human liver disease/cancer with antibodies against TIPRL/LC3/CD133/CD44/CD46, followed by confocal observation." (PMID 34208132, 2021). "Here, we show that the variables TIPRL, LC3, CD133, and CD44 each, excluding CD46, are associated with liver disease patients’ survival." (PMID 34208132, 2021). "This was the first study to report on the association between the CD44 polymorphisms rs8193, rs10836347, and rs13347 and susceptibility to HBV‐related liver disease." (PMID 31301090, 2019). "Interaction of hyaluronan-CD44 is important in numerous inflammatory diseases, such as allergic dermatitis and inflammatory liver disease." (PMID 27184066, 2016). "Therefore, further studies are needed to gain more insight into potential anti-inflammatory strategies for targeting CD44 in liver disease." (PMID 38731968, 2024). "Additionally, our results indicate that SPP1 has a key role in liver disease, where it communicates with T cells expressing CD44." (PMID 38768139, 2024). "These pathophysiological effects of CD44 in the liver suggest that CD44 could be a promising therapeutic target for the treatment of liver disease." (PMID 38731968, 2024). "Hence, this review focuses on the role of CD44 in liver pathology to provide a basic understanding of its involvement in liver disease and suggests the need for further research on CD44 in liver disease, beyond its role in cancer." (PMID 38731968, 2024). "Moreover, gene expression levels of the osteopontin receptor CD44, recently described as an important marker and a key player of liver diseases, including NAFLD, were also determined." (PMID 30818874, 2019). "Because CD44 functions as a receptor, it may provide a convenient therapeutic target in the management of lipid dysregulation in diet-induced liver disease and type 2 diabetes." (PMID 23505504, 2013).
liver disease (continued). "Therefore, gaining an understanding of the sophisticated mechanisms of CD44 may help in the development of treatments that selectively promote liver regeneration while suppressing the pathogenesis of liver disease." (PMID 38731968, 2024). "Hence, to help to expand our knowledge of the role of CD44 in liver disease and highlight the need for further research, this review provides evidence of CD44’s effects on liver physiology and its involvement in the pathogenesis of liver disease, excluding cancer." (PMID 38731968, 2024). "Although CD44 and RHAMM are widely recognized as amplifiers of HA-driven fibrogenic and immunomodulatory signaling in liver disease, recent evidence underscores the importance of inflammatory context in shaping HA–receptor outcomes." (PMID 41155434, 2025). "In line with the role of TIPRL in the expression of LC3, CD133, and CD44, we demonstrate the significant upregulation of TIPRL and LC3 in tissues of hepatocyte-derived liver diseases while being downregulated in cirrhosis, the terminal stage of fibrosis." (PMID 34208132, 2021). "On the other hand, except for cirrhosis and liver tissue degeneration, we determined the upregulation of CD133, CD44, and CD46 in liver disease tissues." (PMID 34208132, 2021). "Considering the differences between cancer and non-cancer diseases and the significant influence of CD44 in the liver, additional studies are required to elucidate the contribution of CD44 to the pathogenesis of liver disease." (PMID 38731968, 2024). "We also determined the significance of CD44 on the OS of liver disease patients in the training set, although not validated in the validation set." (PMID 34208132, 2021). "However, the effect of CD44 activation via cleavage in liver disease has not been fully elucidated." (PMID 38790021, 2024).